MTOR (mechanistic target of rapamycin kinase)
Diseases named in the same sentence as MTOR in open-access papers (continued):
Sharing a sentence is not in itself a finding about the gene and the disease.
cancer (continued). "Since ROS generation induced by EGCG can upregulate AMPK, presumably through upregulation of Ca2+/calmodulin-dependent protein kinase kinase (CaMKK) and/or liver kinase B1 (LKB1), leading to downregulation of mechanistic target of rapamycin kinase (mTOR) which results in anti-cancer effects." (PMID 33027981, 2020). "However, lentiviral overexpression of SESN2 and mTOR inhibitors suppressed cancer cell proliferation, migration, and epithelial–mesenchymal transition." (PMID 32899752, 2020). "Our current study uncovered a novel regulatory network between mTOR and TF in cancer development." (PMID 32923403, 2020). "Moreover, a recent review has highlighted the roles of hypoxia inducible factor 1 (HIF-1) and the PI3K/AKT/mTOR pathway in reprogramming metabolism of cancer cells towards preferential utilization of aerobic glycolysis as an energy source." (PMID 32937954, 2020). "Therefore, targeting of the mTOR/p70S6K pathway is becoming an attractive therapeutic strategy for cancer treatment." (PMID 32111101, 2020). "However, when lactate was used as the primary substrate, the cells were completely resistant to the inhibitors, suggesting that cancer cells able to rely on glycolysis by utilizing lactate are less sensitive to PI3K/mTOR inhibitors." (PMID 33153193, 2020). "By significance analysis, including GO term-enrichment analysis, KEGG pathway analysis and GSEA analysis, LINC00263 might affect cancer progression through the PI3K/AKT/mTOR and NF-κB pathways." (PMID 32195358, 2020). "However, the role of p66ShcA in controlling Ras/MAPK and AKT/mTOR signaling in cancer cells under chronic, yet moderately elevated stress conditions, remains undefined." (PMID 31941526, 2020). "Moreover, inhibition of PI3K/AKT/mTOR pathway in other cancers has been shown not only to directly target cancer cells but also modulate tumor microenvironment and tumor-infiltrated immune cells." (PMID 32483262, 2020). "Hence, medication that can attenuate mTOR activity with subsequent blockade of cell cycle progression, can potentially also block the progression of the prostate cell cycle and cancer growth." (PMID 32539807, 2020). "Furthermore, the AKT/mTOR signaling pathway can also regulate c-Myc to affect the metabolism and growth of cancer cells." (PMID 32685545, 2020). "Taken together, actein may inhibit the metastasis of HER2-positive cancer cells through the AKT/mTOR or Ras/Raf/MAPK signaling pathways." (PMID 32547952, 2020). "Ribosomal protein S6 kinase (p70S6K) and eukaryotic initiation factor 4E binding protein (4E-BP1), downstream effectors of mTOR, are known to regulate protein translation and biosynthesis of lipids and nucleotides, thus endowing cancer cells with the ability of growth and survival." (PMID 32626538, 2020). "Therapy can trigger cell death, arrest of cancer cells at a certain phase of the cell cycle, or induce the emergence of a cancer cell population with activated cell injury repair signature due to signaling pathways PI3K/AKT/mTOR, Jak/STAT, WNT/β-catenin, and others." (PMID 33114182, 2020). "Moreover, genes with AS events in ETMR were involved in developmental processes as well as cancer-related signaling pathways including ErbB, mTOR, and MAPK pathways." (PMID 32971786, 2020). "Moreover, naringin induced autophagy-mediated growth inhibition by downregulating the PI3K/Akt/mTOR cascade via activation of MAPK pathways in AGS cancer cells." (PMID 33381024, 2020). "Metformin is a first-line therapy for treatment of T2D and has shown in numerous studies to produce anti-cancer effects through inhibition of the mammalian target of rapamycin (mTOR) pathway, which is important in controlling cancer cell proliferations and cell growth." (PMID 32369516, 2020). "Moreover, the combined treatment with BEZ235 and chemotherapy drugs, such as cisplatin, trametinib and paclitaxel, provided a synergistic effect by suppressing the Akt/mTOR pathway in cancer." (PMID 32466169, 2020).
cancer (continued). "Recently, researchers have speculated that the AMPK/mTOR signaling pathways are the main axes in regulating the proliferation and survival of cancer cells." (PMID 32375410, 2020). "Due to various gene depletion or mutation (PTEN, PI3KCA, and RTK etc), dysregulation and overactivation of phosphatidylinositol 3-kinase (PI3K)-Akt-mammalian target of rapamycin (mTOR) cascade is detected in NSCLC, which is associated with tumorigenesis and cancer progression." (PMID 33154352, 2020). "This suggests mTOR represents a key target for combinatorial anti-cancer strategies." (PMID 33318517, 2020). "The direct anti-cancer mechanism of metformin is associated with activation of adenosine monophosphate-activated protein kinase (AMPK) and inhibition of the mammalian target of rapamycin (mTOR) activity." (PMID 33198356, 2020). "In conclusion, miR-4634 may act as a tumor suppressor in NSCLC, and to augment the efficacy of RAD001, co-treatment of miR-4634 and RAD001 might be a potential mTOR-targeted cancer therapy strategy for NSCLC patients." (PMID 32753611, 2020). "Indeed mTORC1, together with other components of the PI3K/AKT/mTOR pathway, modulates the expression of a number of proteins involved in glucose import and glycolysis, contributing to cancer metabolic reprogramming." (PMID 32708306, 2020). "It is reported that mTOR is hyperactivated in almost 70% of all human cancers." (PMID 33142217, 2020). "Some vital cancer‐related pathways were shown to be affected by these target genes of circMATR3, including FoxO, mTOR and MAPK signalling pathways, suggesting that circMATR3 might be a potential therapeutic target for HSCC." (PMID 32166857, 2020). "For example, the mTOR pathway is often activated in cancers and may generate therapy resistance followed by Hedgehog pathway inhibition." (PMID 33665161, 2020). "Gene set enrichment analysis revealed several crucial pathways (ERBB signaling pathway, pathways in cancer, MTOR signaling pathway, WNT signaling pathway, and TGF BETA signaling pathway) that may explain the underlying mechanisms of KIRC." (PMID 33133154, 2020). "Moreover, targeting mTOR with rapamycin in the mouse model of experimental bone metastases resulted in a significant attenuation of cancer-induced osteolysis, but had minimal effect on osteoclasts in the cancer-free bones of the same animals." (PMID 32582711, 2020). "Importantly, the PI3K/AKT/mTOR pathway also plays a pertinent role in regulating various aspects of cancer metabolism." (PMID 32226926, 2020). "In addition, GSEA showed that YTHDF2 impacted on multiple cancer signaling pathways, including mTOR pathway, GSK3 pathway, EIF4 pathway, and CHREBP2 pathway." (PMID 33102202, 2020). "Consequently, mTOR kinase inhibitors targeting both mTORC1 and mTORC2 are considered promising anti‐cancer therapies and are being tested in clinical trials, in combination with radiation and chemotherapy." (PMID 32567735, 2020). "Nevertheless, significant amount of work conducted in human cellular models has shown that mTOR inhibition supresses the senescence associated secretory phenotype (SASP), which can disrupt tissues and contribute to age-related pathologies, including cancer." (PMID 32899412, 2020). "Thus, miR-1911-3p functions as a suppressor of mTOR signaling through the regulation of MEAK7 mRNA translation in human cancer cells." (PMID 33364499, 2020). "For example, inhibiting autophagy and increasing the survival of cancer cells may be a consequence of the incorrect activation of the PI3K–Akt–mTOR signaling pathway." (PMID 33066407, 2020). "In this study, we hypothesized that miRNAs regulate mEAK-7 to modify mTOR signaling in cancer cells." (PMID 33364499, 2020). "According to that, mTOR inhibitors could constitute a group of drugs potentially reducing the frequency of post-transplant de novo cancers." (PMID 32222803, 2020). "Additionally, several cancers, such as cervical and breast cancers, are resistant to mTOR inhibitors." (PMID 36046386, 2020).
cancer (continued). "The MTOR signaling pathway mainly regulates cell proliferation and metabolism involved in tumor development and is an important signaling pathway related to human cancer." (PMID 33335853, 2020). "For one thing, Huaier induced human renal clear cell carcinoma cell apoptosis analyzed with flow cytometry by inhibiting the activation of the PI3K/AKT/mTOR/p70S6K/4E-BP1 pathway which is aberrantly activated in many cancers and promotes the growth and proliferation of cancer cells." (PMID 32655761, 2020). "The m6A hyper-methylated genes of Wnt/β-catenin signalling pathway, mTOR signalling pathway, and several cancer-related pathways may contribute to PE." (PMID 32983644, 2020). "Of note, inhibiting mitophagy may be one of the mechanisms of action of Temsirolimus, a mTOR inhibitor already in use for other clinical applications than cancer." (PMID 32548570, 2020). "In addition, the expression of PTEN is often eliminated by epigenetic, genetic, and post-transcriptional modification to up-regulate the PI3K/Akt/mTOR pathway in most malignant tumors." (PMID 32175074, 2020). "Several cancer-related pathways were enriched in the WTC-exposed subjects, including endocytosis, mitogen-activated protein kinase (MAPK), viral carcinogenesis, as well as Ras-associated protein-1 (Rap1) and mammalian target of rapamycin (mTOR) signaling." (PMID 32751422, 2020). "Mycophenolic acid, an immunosuppressant, can inhibit proliferation and induce apoptosis in cancer cells, which may be caused by inhibition of upregulation of CCND1 and the PI3K/AKT/mTOR pathway." (PMID 32733557, 2020). "Some of the therapeutic approaches targeting COX-2 and mTOR in AD and cancer are also discussed." (PMID 32742252, 2020). "SFN may, therefore, be a useful supplement to anti-cancer protocols based on down-regulating the Akt-mTOR signaling cascade." (PMID 32512849, 2020). "Consequently, LAT1 is involved in cancer development and invasion through the mTOR pathway by providing nutrients and participating in oxygen regulation and autophagy." (PMID 33195053, 2020). "In this case, the induction of autophagy by the PI3K/AKT/mTOR inhibitors may suppress the growth of cancer cells." (PMID 33123479, 2020). "Similarly, aberrations in the PI3K/AKT/mTOR pathway are commonly described in aggressive cancers and inhibitors of this pathway can improve outcomes in some patients when combined with paclitaxel." (PMID 32781579, 2020). "As reported, mTOR signaling is enhanced in various types of cancers." (PMID 30754640, 2019). "Thus, we believe that the signal pathway between CEACAM1-S and PI3K (p110δ)/Akt/mTOR can be new alternative of future therapies against epithelial transition from inflammation to cancer." (PMID 31072323, 2019). "Several mTOR inhibitors were successfully tested for the treatment of various cancers." (PMID 31835318, 2019). "The activity of mTOR is frequently upregulated in human cancer." (PMID 31277692, 2019). "Although targeting AMPK/mTOR has become a potential target for cancer treatment, in some cases, AMPK activation might promote cancer." (PMID 30791936, 2019). "High mTOR activity is common in various cancers, including CRC." (PMID 31284426, 2019). "The immunomonitoring performed in this study gives insight into the effects of mTOR inhibition and low-dose oral cyclophosphamide in cancer patients and thereby provides relevant information for the design of future treatments that incorporate or are based on mTOR inhibitors." (PMID 30756132, 2019). "Interestingly, the KEGG annotation analysis highlighted the mTOR signaling pathway, which represents one of the main signaling pathways activated in cancer through important metabolic changes." (PMID 31115969, 2019). "In conclusion, [11C]-pictilisib was first successfully prepared, and it exhibited good potential to identify pictilisib-sensitive tumors noninvasively, which may have a great impact in the treatment of cancers with an overactive PI3K/Akt/mTOR signal pathway." (PMID 31787861, 2019).
cancer (continued). "Thus, activation of the PI3K/AKT/mTOR pathway plays a vital role in cancer disease progression, protein synthesis, and is recognized as one of the key targets for novel treatment approaches." (PMID 31783627, 2019). "For example, the mTOR pathway is a critical pathway that is deregulated in both cancer and PKD." (PMID 31251475, 2019). "In addition, this axis is an essential target for anti-cancer agents, especially in tumors displaying elevated activity of the mTOR pathway." (PMID 31366089, 2019). "Inhibition of the mTOR signaling pathway has become an attractive target for human cancer therapy." (PMID 31665029, 2019). "Moreover, the ATP-competitive mTOR inhibitor Torin1 and PI3K/mTOR inhibitor VS-5584 preferentially reduce CSC levels in multiple mouse xenograft models of human cancer." (PMID 31277692, 2019). "The phosphatidylinositol 3-kinase (PI3K)/AKT/mTOR pathway cascade containing PI3K, AKT, and mTOR is the most frequently altered pathway in human for cancer development, such as cell cycle, cell survival, metabolism, motility, angiogenesis, chemoresistance, and genomic instability." (PMID 31354475, 2019). "Treatment with mTOR inhibitors can reduce high mTOR signaling levels in various cancer types." (PMID 31058839, 2019). "Therefore, pharmacological inhibition of the mTOR signaling pathway is emerging as a useful therapeutic strategy for various cancers." (PMID 31387554, 2019). "Notably, the positive impact of autophagy on cancer therapy is dependent to the stage of cancer and its progression and if mTOR inhibitor pharmaceuticals failed in cancer therapy owing to the acidic pH microenvironment of cancer cells." (PMID 31557936, 2019). "Cancer cells that harbor a subset of those mutations, including C1483F, E1799K, and S2215Y, are hypersensitive to rapamycin, whereas three mutations (A2034V, F2018L, and S2035F) in the FRB domain of mTOR are associated with rapamycin resistance." (PMID 31277692, 2019). "EGFR and HER2 can form homodimers or heterodimers after activation to activate intracellular signaling pathways, such as RAS/RAF/MEK/ERK, PI3K/AKT/mTOR, Src kinase, and STAT transcription factors associated with tumorigenesis, cancer progression, and drug resistance." (PMID 30952931, 2019). "Interestingly, cancer cells treated with the nelfinavir showed reduced mTOR activity and increased ATF4 and SESN2 expression levels." (PMID 31546746, 2019). "The modulation of autophagy is a recurrent trait in cancer cells, as may be expected from its tight regulation by nutrient and energy sensing pathways such as AMPK and mTOR, so frequently altered in cancer." (PMID 31546746, 2019). "It is unclear whether the increased CASC9 expression in cancer cells regulates the expression of mTOR through the regulation of the PI3K/AKT signaling pathway to control autophagy." (PMID 30674868, 2019). "Several studies have demonstrated the relationship between TIPRL and mTOR in cancer." (PMID 31862913, 2019). "In addition, a previous study has indicated that the Akt/mammalian target of rapamycin (mTOR) pathway is involved in regulating the proliferation and apoptosis of cancer cells." (PMID 31376209, 2019). "Overall, deregulated or reprogrammed mTOR signalling is a key signature of cancer cellular metabolism, while the molecular manipulation of the internal and surrounding tumour environment both initiates and sustains cancer cell survival, growth, and proliferation." (PMID 30970654, 2019). "Consequently, intense research efforts are focusing on investigating the PI3K/AKT/mTOR pathway as a promising therapeutic target for cancer treatment in clinical studies." (PMID 31058807, 2019).
cancer (continued). "Since mTOR is considered to be the master regulator of the autophagy pathway, its inhibitors have been investigated for their therapeutic potential in different types of cancers, and autophagy-induction is one of the proposed mechanisms of action." (PMID 30774592, 2019). "The same study demonstrated that LF-derived cathepsin B (CTSB) induced SCD1 overexpression in B16F10 cells via annexin A2 (ANXA2) and the PI3K/Akt/mammalian/mechanistic target of rapamycin (mTOR) pathway, which is critical for cellular metabolism and cancer progression." (PMID 31284458, 2019). "Several cancer tumour cells exhibit constitutive activation of PI3K/AKT/mTOR pathway." (PMID 31653897, 2019). "Since Akt/mTOR pathway can be involved in several important processes identification of active drugs targeting this pathway can be expected to have a major impact on various therapeutic strategies against cancer." (PMID 30813295, 2019). "This pathway acts in synergy with the mTOR signaling in the development of many cancers." (PMID 30866419, 2019). "In nonviral cancers, this is often due to activating mutations upstream of mTOR and/or loss of tumor suppressors such as the phosphatase and tensin homolog (PTEN)." (PMID 30782662, 2019). "In addition, many mTOR inhibitors with different mechanisms of action have been developed, some of which are undergoing clinical trials in variety types of human cancer." (PMID 31277692, 2019). "Therefore, overexpressed HPSs and small HSPs are critically involved in regulating cell signaling pathways (e.g., PI3K/Akt/mTOR), ROS production, the cell cycle, and apoptosis in cancer cell proliferation." (PMID 31557887, 2019). "The PI3K/AKT/mTOR signaling is pivotal in regulation of gene transcription, invasion, proliferation, cell survival, and central in the metabolism through regulation of enzymes like Glyoxalase 2 (Glo2) and glyoxalase 1 (Glo1) promoting cancer progression." (PMID 31850214, 2019). "Aspirin also activates AMPK and inhibits mTOR and FA synthesis in cancer cell lines." (PMID 31921661, 2019). "Moreover, PI3K/AKT/mTOR, an important regulatory pathway upstream of autophagy, also plays a key regulatory role in the development of cancer." (PMID 31835352, 2019). "In addition, AMPK is involved in cancer proliferation, metastasis, and drug resistance through regulating mTOR signaling." (PMID 31402869, 2019). "Interestingly, the presence of PIK3CA mutations is associated with better treatment response to PI3K/AKT/mTOR pathway inhibitors, suggesting that this genetic alteration may serve as a marker for personalized medicine in order to predict treatment outcomes for this cancer entity." (PMID 31058807, 2019). "mTOR (mammalian target of rapamycin) is a serine/threonine kinase, which controls the various acts of our body such as cell growth, survival, metabolism, is upregulated in various cancer." (PMID 31030499, 2019). "The discovery of deregulation of pre-RC component CDC6 by mTOR signaling might reveal the mechanism of the promotion of genome instability and heterogeneity of cancer cells by the PI3K signaling pathway." (PMID 31285446, 2019). "Consequently, mTOR is being actively pursued as a potential anti-cancer target leading to the emergence of rapamycin and rapalogs as potential anti-cancer agents." (PMID 31856761, 2019). "These signals consist of Ras/Raf/MEK/ERK and Ras/PI3K/Prime Time Entertainment Network (PTEN) / Protein kinase B (AKT, also known as PKB) / mammalian target of rapamycin (mTOR) signaling cascades, and are known to play a significant role in regulating cancer cell growth and survival." (PMID 31771104, 2019). "All these results suggest that PC1 interacts in vitro with the mTOR pathway in cancer cells." (PMID 31251475, 2019). "However, it is known that 1-MT can reactivate the mTOR activity inhibited by TRP depletion in cancer microenvironment." (PMID 31417567, 2019).